TAP1 (transporter 1, ATP binding cassette subfamily B member)
Diseases named in the same sentence as TAP1 in open-access papers (continued):
Sharing a sentence is not in itself a finding about the gene and the disease.
cervical carcinoma (20 papers, 1994 to 2025). A carcinoma arising from either the exocervical squamous epithelium or the endocervical glandular epithelium. "miR-346 was demonstrated to directly target TAP1 and thereby reduce HLA class I expression in non-small cell lung cancer cells and cervical cancer cells." (PMID 38539461, 2024). "P. bivia has been shown to upregulate proinflammatory (LAMP3, STAT1, and TAP1) genes in cervical cancer." (PMID 35928983, 2022). "Single-nucleotide polymorphisms (SNPs) in TAP1 and TAP2 affected their expression and were associated with cervical cancer in the Chinese Han population." (PMID 35837087, 2022). "Immunological methods were used to evaluate the expression of TAP1 protein in ovarian and cervical cancer, and Kaplan–Meier analysis was used to analyze the prognostic value of TAP1." (PMID 34957213, 2021). "To test this, we compared the expression levels of TAP1 between cancer stem cell-like properties (e.g., spheroids) and adherent cells, using cervical cancer cell lines, HeLa, CaSki and SiHa." (PMID 28402962, 2017). "In particular, we have previously shown that downregulation of TAP1, LMP7 and ERAP1 expression is associated with decreased survival in HPV-mediated cervical carcinoma in Dutch patients." (PMID 25796583, 2015). "A decreased level of TAP1 was related to various cancers, like colon, lung, and cervical cancer." (PMID 34047812, 2021). "By co-culturing a cervical cancer cell line with P. bivia, we confirmed that three out of the ten top predicted genes in the transkingdom network (lysosomal associated membrane protein 3 (LAMP3), STAT1, TAP1), all regulators of immunological pathways, were upregulated by this microorganism." (PMID 30294508, 2018). "In order to investigate whether these changes are associated with biological behaviour of the tumours, 20 cervical carcinomas were analyzed for MHC (HLA-A, HLA-B/C, HLA-DR) and TAP-1 expression in the primary tumours and in lymph node metastases by immunohistochemistry." (PMID 8198988, 1994). "Eleven non-synonymous, coding SNPs in the TAP1, TAP2, LMP2, LMP7 and ERAP1 genes were genotyped in cervical carcinoma patients and healthy controls from two distinct Indonesian populations (Balinese and Javanese)." (PMID 25796583, 2015). "By bisulfite sequencing approach, we identified target CpG islands methylated at the gene promoter region of TAP1, TAP2, LMP7, tapasin and ERp57 in cervical carcinoma cells." (PMID 23024775, 2012).
breast carcinoma (19 papers, 2017 to 2025). "TAP1 overexpression might be an indicator of aggressive breast cancer and was also significantly associated with poor prognosis in colorectal cancer." (PMID 35123499, 2022). "have suggested that epigenetic silencing of TAP1 in Aldefluor + breast cancer stem cells contributes to the enhanced survival under immune pressure." (PMID 36419887, 2022). "Studies also reported that a higher expression of TAP1 mRNA was found in stage II breast tumors and an increased level of expression was identified in high-grade breast cancers." (PMID 34047812, 2021). "TAP1 gene expression levels were significantly higher in females having breast cancer than normal counterparts (p = 1.62e-12)." (PMID 34047812, 2021). "It has been reported that epigenetic silencing of antigen peptide transporter 1 (TAP1) gene in breast cancer stem cells promotes immune evasion." (PMID 30915120, 2019). "We showed that higher levels of TAP1 and TAP2 were present in high-grade breast carcinoma and that TAP1 was expressed at higher levels in stage 2 tumors than in stage 1 tumors." (PMID 29091951, 2017). "High levels of TAP1 positively correlated with longer relapse-free survival in patients with breast cancer who underwent chemotherapy." (PMID 29091951, 2017). "The results of this study contradict a previously published report investigating TAP1 and TAP2 levels in 53 patients with breast carcinoma, as well as a report investigating TAP1 levels in primary vs metastatic breast cancer." (PMID 29091951, 2017). "Further, cancer may exhibit varied TAP1 expression levels and clinical outcomes at different stages; for example, in stage 1 and 2 breast cancer, TAP1 expression is reduced, while the trend is reversed in stage 3 and 4 disease; however, TAP1 was considered a protective factor in our study." (PMID 36759763, 2023). "Previously, we observed in a basal breast cancer network a module formed by PSMB9, TAP1, and UBE26 genes among others." (PMID 30761130, 2019). "In this study, we investigated the immunohistochemical expression of TAP1 and TAP2 in 160 patients with breast cancer and correlated their expression levels with clinicopathologic parameters." (PMID 29091951, 2017). "The present study investigated the levels of TAP1 and TAP2 in 480 breast cancer specimens representing 160 patients with breast cancer." (PMID 29091951, 2017). "Our study is the first to utilize TMAs to examine TAP1 and TAP2 levels of 480 breast cancer specimens from 160 female patients with breast cancer." (PMID 29091951, 2017). "Both TAP1 and TAP2 immunohistochemical expression levels correlated significantly with breast cancer characteristics (P < .001)." (PMID 29091951, 2017). "Our study has shown the opposite, with TAP1 and TAP2 being expressed at lower levels in early stages of breast cancer." (PMID 29091951, 2017). "The expression levels of TAP1 and TAP2, as measured by the quick score, were positively correlated in breast cancer specimens." (PMID 29091951, 2017). "The level of TAP1 could affect the survival time of patients with oral squamous cell carcinoma (SCCOT) and breast cancer, and may serve as a tumor marker for the early diagnosis and follow-up of SCCOT." (PMID 34957213, 2021). "We selected a low concentration of IFNγ (1 ng/mL) that induces STAT1 transcriptional responses (β2M, Tap1) but does not impair breast cancer cell growth." (PMID 34083537, 2021). "We have seen high protein levels of both TAP1 and TAP2 in high grade breast cancer before." (PMID 34047812, 2021). "Both TAP1 and TAP2 overexpression in breast cancer might be an indicator of an aggressive breast tumor." (PMID 29091951, 2017). "In early-stage breast cancer, the levels of TAP1 expression reached low to negative, which may contribute to evading the attack of the immune system during tumor formation." (PMID 36419887, 2022).
breast carcinoma (continued). "Notably, downregulation of TAP1 and TAP2 has been described as an immune evasion mechanism in gliomas, a subtype of breast cancer, and murine fibroblasts after oncogenic transformation, similar to the downregulation of β2-Microglobulin in diffuse large B cell lymphomas and colorectal carcinomas." (PMID 35681710, 2022). "In case of breast cancer, GSE9195 and GSE1456-GPL96 sets provided data that patients with decreased expression of TAP1 gene (n = 57 and n = 139 respectively) had significant higher relapse-free survival in comparison with the ones with a greater expression of TAP1 (n = 20, for both)." (PMID 34047812, 2021). "Our results indicate that these strategies may not be necessary in advanced stages and higher grades of breast cancer, which already display the TAP1 and TAP2 subunits." (PMID 29091951, 2017). "Because TAP1 and TAP2 are both located on chromosome 6 and are under the control of IFN-γ to form a heterodimer in the endoplasmic reticulum membrane, we asked whether the expression of these subunits correlated with each other in the breast cancer specimens." (PMID 29091951, 2017).
viral infection (18 papers, 2005 to 2026). "Consistent with previous reports, we observed that IFN-β expression was dramatically elevated by TAP1 expression, implying that the inhibition of viral infection by TAP1 is closely associated with the IFN signaling pathway." (PMID 33925089, 2021). "The expression of TAP1 is usually at a low level but significantly upregulated in response to IFN stimulation or viral infections." (PMID 33925089, 2021). "Taken together, TAP1 can broadly inhibit viral infections through activating the TBK1-IRF3 -mediated IFN-β production." (PMID 33925089, 2021). "Overall, these data indicated that TAP1 affected viral infections by regulating the TBK1/IRF3 signal pathway." (PMID 33925089, 2021). "Furthermore, polymorphisms in TAP1 appear to influence the selection of antigenic peptides and the transport process to the rough endoplasmic reticulum, for their subsequent presentation to T lymphocytes, an essential process against viral diseases and tumor processes." (PMID 33507546, 2021). "In this study, we investigated the function of TAP1 against broadly viral infections through activating unreported signaling pathways, the TBK1-IRF3-mediated type I interferon production." (PMID 33925089, 2021). "In corneal endothelial cells, the antigen processing machinery include the MHC class I, LMP2, TAP1, and β2 microglobulin that are upregulated after a viral infection." (PMID 34389779, 2021). "We also observed that the level of IFN-β mRNA in the TAP1 overexpression group was significantly improved in response to various viral infections, and the elevation of IFN-β protein expression was further confirmed by ELISA." (PMID 33925089, 2021). "All these studies suggested that up-regulation of TAP1 gene expression played an important role in immune defense prevent bacterial and viral infections." (PMID 24955792, 2014). "If so, the question remains as to why, if equal amounts of antigen expression in CMT.64 and CMT.TAP1,2/Kb (by viral infection) were taken up by DCs, do differences in cross-priming explain the differences in T cell responses." (PMID 18769733, 2008). "The upregulated genes associated strongly with microglial activation and included antigen presentation genes (Tap1, B2m) and activation genes (Ccl12, IL-34 and Icam1) that occur in neurodegenerative disease, brain injury and viral infection, and are NF-κB regulated." (PMID 35464428, 2022). "The direct inhibition of viral infection by TAP1 was verified by plaque assay in Vero cells." (PMID 33925089, 2021). "Additionally, immune response pathways, including antigen processing and presentation, viral myocarditis were significantly enriched, with key molecules such as HLA, B2M, and TAP1/2, suggesting that viral infections trigger immune-related processes in neuronal cells." (PMID 40166347, 2025). "Previous studies showed that TAP1 might play a role against viral infection." (PMID 33925089, 2021). "TAP1 and TAP2 are essential in assembly and expression of HLA class I proteins for subsequent generation of CTL-mediated cellular immune response against viral infection and transformed cells." (PMID 31732831, 2020). "We hypothesize that over-expression of transporters associated with antigen processing (TAP1 and TAP2), components of the major histocompatibility complex (MHC) class I antigen-processing pathway, enhances antigen-specific cytotoxic activity in response to viral infection." (PMID 16389301, 2005). "Analysis of TAP1 expression and global gene expression profiles in patients with UVM showed that DEGs were closely related to various immunity-related signaling pathways, such as viral infection and defense response." (PMID 36774490, 2023). "The viral infection resulted in a 30% decrease of mean GFP fluorescence intensity, while approximately 70% and 50% reduction of TAP2-N-GFP and TAP1 protein levels, respectively, could be demonstrated by immunoblotting." (PMID 31817841, 2019).
viral infection (continued). "Patients with inherited CD8, TAP1, TAP2, TAPASIN, or β2-microglobulin deficiencies, all of whom have low levels of HLA-I in all cell types tested and low counts of blood CD8+ T cells, are not prone to viral infections either." (PMID 36736301, 2023).
ovarian carcinoma (16 papers, 2016 to 2024). A malignant neoplasm originating from the surface ovarian epithelium. "Our results showed that TAP1 was upregulated in ovarian cancer cell lines and was associated with poor prognosis." (PMID 34957213, 2021). "In ovarian cancer, the expression of TAP1 is related to MEF2A, LEF1, while MEF2A can promote tumor cell metastasis by inducing epithelial-mesenchymal transformation and activating Wnt/β-catenin signal pathway." (PMID 36419887, 2022). "Researchers were trying to find reliable immune-related prognostic genes in ovarian cancer, including TAP1 and CXCL13." (PMID 34631788, 2021). "In a previous study, we saw that TAP1 was seen to be correlated with overall survival for high-graded serous ovarian cancer but then again, we are considering just ovarian cancer in our study." (PMID 34047812, 2021). "Primarily, the data-focused that indifferent to the single ovarian cancer difference in the expression, high TAP1 expression is in a positive correlation with the low survival rate in breast, lung, and liver cancers." (PMID 34047812, 2021). "To date, some studies have shown the significance of TAP1 or CXCL13 as reliable immune-related prognostic genes in ovarian cancer." (PMID 34631788, 2021). "The expression of the TAP1 gene in normal tissue was compared with tissues in patients with different clinical outcomes for breast, liver, lung, and ovarian cancers." (PMID 34047812, 2021). "The promoter methylation of the TAP1 gene in normal tissue was compared with tissues in patients with different clinical outcomes for breast, liver, lung, and ovarian cancer." (PMID 34047812, 2021). "Compared with normal tissues, cancer tissues showed a significant increase in the expression of TAP1, and TAP1 expression was related to the poor prognosis of cancers such as ovarian cancer." (PMID 34957213, 2021). "We focused on the expression of TAP1 in four cancers kinds, breast, liver, lung, and ovarian cancers." (PMID 34047812, 2021). "In a recent study, pathway and gene ontology (GO) features correlated to the TAP1 gene were analyzed in breast, lung, liver, and ovarian cancer, in which the cytokine–cytokine receptor pathway and chemokine signaling pathway are the most significant pathways influenced by TAP1." (PMID 35806187, 2022). "In ovarian cancer, overexpression of TAP1 in OC patients leads to a poor prognosis." (PMID 36419887, 2022). "TAP1 and CXCL13 were risk factors that affect the prognosis of ovarian cancer." (PMID 34631788, 2021). "Finally, a nomogram model for advanced ovarian cancer based on TAP1 and CXCL13 was established for the first time." (PMID 34631788, 2021). "RNA interference (RNAi) was used to verify the effect of TAP1 on ovarian cancer." (PMID 34957213, 2021). "On the other hand, the analysis of dataset GSE26712 and GSE26712 of PrognoScan showed significantly lower OS and DFS of ovarian cancer, for the lower TAP1 mRNA expression (n = 111 and n = 149, respectively) in contrast with the higher levels of counterparts (n= 74 and n = 36, respectively)." (PMID 34047812, 2021). "An in vitro study with one endometrial cancer and two ovarian cancer cell lines harboring JAK1 frameshift mutations demonstrated that JAK1 mutations impede STAT1 posphorylation and upregulation of antigen presenting machinery components LMP2 and TAP1." (PMID 27213585, 2016). "The levels of expression of antigen expression genes TAP1, TAPBP, B2M, and HLA-A (the human ortholog of the mouse H2-D1 gene) were shown to predict longer patient survival in colon and ovarian cancers." (PMID 39388288, 2024). "VPS13B, TBC1D22A, PPP3CA, CUX1 and PPP1R15A were identified as poor prognostic genes of cisplatin resistance in ovarian cancer, while PLGRKT, CDKAL1 and TAP1 were identified as good prognostic genes." (PMID 39103807, 2024).
ovarian carcinoma (continued). "Through biological information screening, RT-qPCR and WB verification, it was found that VPS13B, TBC1D22A, PPP3CA, CUX1 and PPP1R15A were highly expressed in cisplatin-resistant tissues of ovarian cancer, while PLGRKT, CDKAL1 and TAP1 were low expressed." (PMID 39103807, 2024). "VPS13B, TBC1D22A, PPP3CA, CUX1 and PPP1R15A were identified as poor prognostic genes for cisplatin resistance in ovarian cancer, while PLGRKT, CDKAL1 and TAP1 were identified as good prognostic genes." (PMID 39103807, 2024). "TAP1 was also overexpressed in ONCOMINE database for breast, liver and ovarian cancers but had a contradiction with other databases in the case of lung cancer." (PMID 34047812, 2021). "We have found two immune-related genes, just TAP1 and CXCL13, which can be used as independent prognostic factors for ovarian cancer." (PMID 34631788, 2021). "Various enrichment analyses were used to study the correlation between TAP1 and key transcription factors using the Kyoto encyclopedia of genes and genomes (KEGG) pathway in ovarian cancer." (PMID 34957213, 2021). "Meanwhile, TAP1 mRNA and CXCL13 mRNA levels were significantly elevated in ovarian cancer tissues compared to normal ones." (PMID 34631788, 2021). "Moreover, the expression of TAP1 and CXCL13 were indeed increased in ovarian cancer tissues through experimental verification." (PMID 34631788, 2021). "Although the positive correlation between TAP1 and CXCL13 was weak in ovarian cancers according to the cBioPortal database, some studies still screened that they can be both used as prognostic markers of ovarian cancer." (PMID 34631788, 2021). "In addition, a significantly negative correlation between TAP1 and survival in breast, lung, liver, and ovarian cancer is revealed." (PMID 36685901, 2022). "In patients with ovarian cancer, TAP1 protein abundance was negatively correlated with survival time and significantly correlated with immune infiltration and poor prognosis.Therefore, there is no consistent relationship between TAP1 expression and patient prognosis in different cancer types." (PMID 36774490, 2023).